ACSL4 (acyl-CoA synthetase long chain family member 4)
Diseases named in the same sentence as ACSL4 in open-access papers (continued):
Sharing a sentence is not in itself a finding about the gene and the disease.
neurodegenerative disease (5 papers, 2022 to 2025). A disorder of the central nervous system characterized by gradual and progressive loss of neural tissue and neurologic function. "In Huntington’s disease models, ALOX5 has been identified as a key factor in HTT-Q94-induced, ACSL4-independent ferroptosis, emphasizing its independent role in ferroptosis, particularly in neurodegenerative diseases." (PMID 40191227, 2025). "Inhibition of ACSL4 promotes the differentiation of neural stem cells into neurons, suggesting its potential as a therapeutic target for neurodegenerative diseases." (PMID 41288931, 2025). "Triacsin C is a natural product and broad-spectrum ACSL inhibitor that inhibits ACSL4 activity and has potential therapeutic effects on various types of tumors and results in improvement in some neurodegenerative diseases." (PMID 37372148, 2023). "Some drugs and regulatory factors have rescued neurodegenerative diseases by inhibiting ACSL4-dependent ferroptosis." (PMID 37372148, 2023). "Thus, ACSL4 inhibitors hold potential therapeutic value in treating neurodegenerative diseases and cancer." (PMID 40191227, 2025).
immune disorder (2 papers, 2023). "Pivotal markers such as acyl-CoA synthetase long-chain family member 4 (ACSL4) are known for their significant regulatory effects on ferroptosis in many immunity disorders." (PMID 37884942, 2023).
nervous system diseases (2 papers, 2023). "In this review, we will mainly discuss the role of ACSL4 in the process of ferroptosis and investigate the effect of ACSL4 on nervous system diseases or injuries." (PMID 37373168, 2023).
neurodevelopmental disorder (2 papers, 2022 to 2026). A behavioral and cognitive disorder with onset during the developmental period that involves impaired or aberrant development of intellectual, motor, or social functions. "Notably, although these genes have not been demonstrated to be directly associated with ALS in previous studies, NR4A1 and DRD4 are reported in AD, ACSL4 seems to be a biomarker of ferroptosis, and SETD1B is associated with syndromic neurodevelopmental disorder." (PMID 35873477, 2022).
adenocarcinoma (1 paper, 2024). A common cancer characterized by the presence of malignant glandular cells. "In primary lung tumors, a higher expression of ACSL1, ACSL4, and ACSL5 was significantly correlated with adenocarcinoma (ADC)." (PMID 38539505, 2024).
bacterial infections (1 paper, 2024). "Our findings further elucidate the role of IRF7 in regulating ferroptosis by transcriptionally regulating ACSL4 expression, suggesting that IRF7 could be a promising therapeutic target to protect BMSCs from bacterial infections (as illustrated in the schematic diagram)." (PMID 39166412, 2024).
genetic disorders (1 paper, 2023). "In addition, the possibility that ACSL4 plays a role in genetic disorders cannot be ignored, as ACSL4 deletion mutations have been reported in a family with Alport disease (also known as eye-ear-kidney syndrome)." (PMID 37373168, 2023).
infectious disease (1 paper, 2023). A disorder directly resulting from the presence and activity of a microbial, viral, or parasitic agent in humans. "There is a possibility that an increase in PE containing PUFA occurs in various infectious diseases, with induction of ACSL4 as a common mechanism." (PMID 37648726, 2023).
intestinal diseases (1 paper, 2025). "Our findings establish the ACSL4/NF-κB axis as a central mechanism in cadmium-induced pathology, highlighting sodium octanoate as a potential therapeutic intervention for pollutant-induced intestinal disorders." (PMID 40901058, 2025). "This discovery not only provides a new perspective for understanding the deep mechanism of cadmium-induced intestinal inflammation but also suggests that ACSL4 may become an important target for the prevention and treatment of intestinal diseases related to environmental toxins in the future." (PMID 40901058, 2025).
ACSL4 also shares sentences with these, for which no sentence is quoted: leukemia (5 papers); liver (3); multiple myeloma (3); acute myocardial infarction (2); chronic myeloid leukemia (2); coronary atherosclerosis (2); cutaneous squamous cell carcinoma (2); ischemic disease (2); acute lung injury (1); adrenocortical adenomas (1); age (1); alcoholic liver diseases (1); Allergy (1); Arthritis (1); astrocytoma (1); axonal neuropathy (1); Bovine mastitis (1); brain cancer (1); brain tumor (1); Calicivirus Infection (1); cervical squamous cell carcinoma (1); chronic obstructive pulmonary disease (1); co-infection (1); cortical dysplasia (1); diabetic foot ulcer (1); diffuse large B-cell lymphoma (1); dry eye (1); E. coli infections (1); emphysema (1); esophageal squamous cell carcinoma (1).
A further 45 diseases each share a sentence with ACSL4 in 1 paper.